TNF (tumor necrosis factor)
Diseases named in the same sentence as TNF in open-access papers (continued):
Sharing a sentence is not in itself a finding about the gene and the disease.
tumor (continued). "In particular, mast cells play a role in tumor initiation, maintenance, and growth by synthesizing and secreting matrix metalloproteinases, various cytokines (IL6 and TNFα), and multiple mitogens [vascular endothelial growth factor precursor (VEGF) and platelet-derived growth factor (PDGF)]." (PMID 33244317, 2020). "As observed in in vitro testing of cancer cell lines, the lack of efficacy of LCL161 in this study correlated with lack of basal production and insensitivity of tumor cells to TNF." (PMID 32053868, 2020). "Similarly, cytokine-engineered oncolytic viruses, such as the TNF-armed attenuated oncolytic Vesicular Stomatitis Virus (VSV∆51), combined with the SM LCL161, slowed tumor growth and improved survival rates in mouse models of solid tumors." (PMID 32053868, 2020). "On the contrary, TNF-α induced Met expression in neutrophils, which could release nitric oxide upon HGF stimulation, thereby killing tumor cells." (PMID 32422991, 2020). "Therefore, the inflammatory cytokine TNFα coordinates both EMT and tumor immune evasion by using NF-κB signaling (see also the previous paragraph)." (PMID 33324403, 2020). "Furthermore, they modulate pro-tumorigenic inflammation through secretion of IL-1, IL-6, TNF-α, TGF-β, and CCL2, favoring tumor growth, angiogenesis, invasion and metastasis." (PMID 32499779, 2020). "Additionally, they can promote the release of inflammatory factors such as TNF-α, MIP, and MCP and participate in the formation of an anti-tumor inflammatory microenvironment." (PMID 33363026, 2020). "A negative correlation was noted between MCF-7 cell viabilities and M1/M2 cytokine secretion ratios ((IL-6 + TNF-α)/IL-10) in the corresponding MCM, suggesting that increases in M1 macrophages in the tumor microenvironment might inhibit MCF-7 cell growth." (PMID 32308723, 2020). "One showed that the trained animals did not undergo any changes in tumor mass compared to their matched control; however, muscle mass was preserved and inflammatory markers such as TNFα and IL-6 were reduced in the plasma of animals submitted to RT." (PMID 33613297, 2020). "Tumor angiogenesis is significantly enhanced in obese state, mainly due to the elevated circulating pro-angiogenic/-inflammatory factors released from adipocytes, such as VEGF, IGF-1, MCP-1, IL-1, TNF, etc24." (PMID 31996731, 2020). "Tumor angiogenesis is regulated by a variety of cytokines including VEGF, placenta growth factor (PLGF), transforming growth factor-β (TGF-β), tumor necrosis factor-α (TNF-α), platelet-derived growth factor (PDGF), fibroblast growth factor (FGF), and angiopoietin." (PMID 33363174, 2020). "The tumor necrosis factor (TNF) ligand family members TNFα, Fas ligand (FasL) and Tumor-necrosis-factor related apoptosis ligand (TRAIL) are major immunoregulatory cytokines of the tumor microenvironment, also found to be important SASP components." (PMID 32370259, 2020). "We detected cytokines such IL-6, TNF-α, and TGF-β in mouse serum, and showed that the developed nanospheres induced an immune response, which may have regulated tumor killing." (PMID 32636744, 2020). "However, the lower production of pro-inflammatory cytokine TNFα and IFNγ in CD4+T cells or CD8+T cells in the tumor-bearing mice were significantly reversed by DMM treatment." (PMID 32596169, 2020). "We also cultured mouse and human Teff cells in conditioned medium and assessed the expression of effector molecules, including granzyme B, tumour necrosis factor alpha (TNF-α) and interferon gamma (IFN-γ), all of which are important in mediating the tumour-cell-killing activity of Teff cells." (PMID 32694789, 2020). "Macrophages are one of the main sources of TNFα and are among the most abundant non-neoplastic cells in the tumor microenvironment." (PMID 32332865, 2020).
tumor (continued). "Although IL-1β, IL-6, and TNF-α have been shown to be regulated by MK2 signaling, cytokines often act in autocrine or paracrine manners to regulate production of other cytokines in the tumor microenvironment." (PMID 32216812, 2020). "A TNF‐based AcTakine targeted to CD13 enables selective activation of the tumor neovasculature without any detectable toxicity in vivo." (PMID 31912630, 2020). "Besides, Munich and colleagues used murine BMDC DEVs loaded with TNF, FasL and TRAIL describing that these vesicles had the ability to directly kill B16 tumor cells ex vivo by promoting apoptosis, and also induced NK cell activation and their IFNγ production." (PMID 33260499, 2020). "As TNF-α from DCs is considered immunostimulatory, this then supports an extensive immunosuppressive phenotype induced by the colonic TME, in particular as shown by DC IL-12p70 inhibition, a requirement for optimal anti-tumour immunity." (PMID 32552799, 2020). "In H22 tumor-bearing mice, oral administration of CSP resulted in increased body weights; peripheral white blood cell counts; thymus and spleen indices; and serum IL-2, IL-6, and TNF-α levels in vivo." (PMID 32595757, 2020). "TDEVs not only contain the typical exosomal markers, like tetraspanins (CD81, CD63), ESCRT proteins (TSG101), heat shock proteins (HSC70), but also tumor-specific markers such as TAAs (Her2/Neu, Mart1, TRP, GP100), MHC molecules, TNF, Fas Ligand, CD73 or Galectin-9." (PMID 33260499, 2020). "Consequently decreasing IFN-γ+ and TNF-α+ effector CD8+ T TILs and in tumor-draining lymph nodes, resulting in an immunosuppressive environment." (PMID 33335860, 2020). "While numerous pathways, such as T cell activation and proliferation, Leukocyte chemotaxis, and Response to TNF, implicate anti-tumor activity, ERK signaling in macrophages has been shown to be tumor-promoting by exerting both anti-inflammatory and pro-invasive properties." (PMID 33072601, 2020). "About 75% of NENs with more than 25% positive cells in the >10% Ki-67 group had increased TNF-α levels, as opposed to 31.4% in the Ki-67 ≤10% tumor group." (PMID 32156252, 2020). "Similarly, breast cancer exosomes were found to induce macrophage-mediated secretion of the cytokines TNFα, IL6, and MCP1, which stimulate tumor progression and metastasis." (PMID 32547552, 2020). "In addition, the combined treatment of FimH and OVA markedly increased intracellular IFN-γ- and TNF-α-producing OT-I and OT-II cells in the B16-OVA tumor." (PMID 32132528, 2020). "TNF produced by immune cells contributes to SM efficacy, particularly against tumours that do not secrete TNF following degradation of IAPs." (PMID 31947615, 2020). "Indeed, typical sEVs can be derived from expanded γδ T cells ex vivo and these sEVs express several of the cytotoxic markers (including NKG2D, FasL, TNF-α, and IFN-γ) of the parental cells and are able to inhibit tumor growth." (PMID 32765528, 2020). "Similarly, an increase in the TNF-α and IL-12 cytokine levels and a decrease in TGF-β cytokine level were observed in the TME of TC-1 tumor-bearing mice treated with cisplatin and AnxA5 as compared to those treated with cisplatin only." (PMID 32111835, 2020). "TNF (Tumor Necrosis Factor) is a kind of cytokine which can directly kill tumor cells but has no obvious toxicity to normal cells." (PMID 32963574, 2020). "The intravenous injection of dendriplexes resulted in the specific expression of TNF-α in tumor tissue with very low levels of non-specific gene expression in the liver." (PMID 32183434, 2020). "For example, TNF or chemotherapy (mitoxantrone/oxaliplatin)-driven necroptosis in cancer cells releases several different DAMPs such as ATP and HMGB1, thereby facilitating tumor-regressive anticancer immunity." (PMID 32752206, 2020). "Furthermore, anti-TNF-α and anti-IL1-R treatment also reduced tumor growth, suggesting indirect effects of inflammation as a determinant of tumor burden in driving atrophy." (PMID 33329046, 2020).
tumor (continued). "The expression of surface molecule CD86 and major histocompatibility complex II (MHC II), as well as the secretion of cytokine tumor necrosis factor-α (TNF-α) and toxic molecules like nitric oxide are elevated by M1 macrophages, which are typically described as tumor-killing macrophages." (PMID 32512803, 2020). "Furthermore, tumor-derived HSPs activate TLR4 signaling in TAMs to produce cytokines that are beneficial to tumor growth, such as TNF-α and VEGF." (PMID 33224886, 2020). "Importantly, tumor-infiltrating CD8+ T cells in SMF-treated mice produced more antitumor granules and cytokines, including granzyme B, IFNγ and TNFα, than their counterparts from control mice." (PMID 32884074, 2020). "To investigate whether emodin induced necroptosis in vivo, we measured the levels of TNF-α, RIP1, RIP3 and MLKL in tumor tissues treated with emodin or saline." (PMID 30924024, 2020). "Moreover, detection of inflammatory cytokines showed that Kejinyan decoction downregulated TNF-α, IFN-γ, IL-6, as well as IL-4, IL-13 in tumor microenvironment." (PMID 32943999, 2020). "In our studies, MSCs-IL10 exhibited a strong inhibitory effect on the growth of PANC-1 subcutaneous tumors, and can well inhibited secretion of TNF-α and IL6, the pro-inflammatory cytokines and tumor angiogenesis, so that tumor-bearing mice had longer survival." (PMID 32742480, 2020). "Others have described modulation of cytokine production of IL-1α, IL-1β, IL-2, IL-4, IL-6, IL-8, IL-10, IL-17A, TNF-α, and IFN-γ on tumor cells treated with conventional PDT, but their increase or decrease seems to highly depend on the cell line and PDT protocol used." (PMID 32326519, 2020). "Moreover, the TNF-α and IFN-γ-producing tumor-infiltrated CTLs were markedly increased by the combined treatment of anti-PD-L1 Abs and FimH." (PMID 32132528, 2020). "IL-6, similar to TNF-α, promotes the transformation of noncancer cells into cancer stem cells while regulating the biological activity of tumor cells, leading to cell proliferation or distant metastasis." (PMID 32149121, 2020). "Similarly, the supernatants from tumor cells treated with NDV-MIP3α or NDV-WT led to increased secretion of IFN-γ and TNF-α in DCs." (PMID 32759233, 2020). "Accordingly, hypoxia, TNF-α, TGF-β, IL2-STAT5, and the mTORC1 pathways were enriched in recurrent tumor cells, suggesting that these pathways may be critical for the OS chemotherapeutic resistance and tumor recurrence." (PMID 33303760, 2020). "Tumor produce a vast number of cytokines (for example, VEGF-A, TGF-β, TNF-α) and extrude different microvesicles, which act in a systemic fashion, modulating the behavior of host cells in distant tissues, most notably bone marrow, spleen and pre-metastatic niches." (PMID 32286443, 2020). "They secrete vascular endothelial growth factor (VEGF) to promote tumor angiogenesis, secrete matrix metalloproteinases (MMPs) to facilitate tumor invasion, and secrete cytokines such as tumor necrosis factor (TNF)-α and IL-8 to stimulate immune tolerance and promote tumor progression." (PMID 32626535, 2020). "TNFα-potentiated upregulation of the monocyte chemoattractant MCP-1 has been reported in IgE-mediated parasite response, and in the tumour microenvironment following systemic IgE treatment in vivo associated with significant recruitment of macrophages towards tumour lesions." (PMID 33203088, 2020). "Functionally, while TCF1– terminally exhausted tumor-infiltrating CD8 lymphocytes (TILs) expressed more interferon-γ (IFN-γ) and granzyme B, TCF1+ stem-like TILs were more polyfunctional, as shown by co-producing IFN-γ, tumor necrosis factor α (TNFα) and IL-2." (PMID 32899486, 2020). "Notably, it was recently shown that treatment of mice with tumor necrosis factor (TNF) inhibitors concomitantly with anti-PD-1 and anti-CTLA-4 antibodies ameliorates immune-related colitis and, in addition, improves anti-tumor efficacy." (PMID 31947592, 2020).
tumor (continued). "Of note, when the in vitro expanded DOT cells were transferred in vivo, they have ability of producing abundant IFN-γ and TNF-α (but no IL-17), and displayed high capacity to inhibit tumor growth and prevent dissemination in xenograft model of CLL." (PMID 32413966, 2020). "The anti-tumor activity of TAMs is implemented by the upregulation of FAO that is a key feature of M2 macrophage metabolism, however increased pro-inflammatory cytokines (TNF, IFNγ and CCL2) in the serum of mice were also detected." (PMID 32486098, 2020). "TAMs participate in the tumour angiogenesis by secreting pro‐angiogenic factors, including VEGF‐A, EGF, PlGF, TGF‐β, TNF‐α, IL‐1β, IL‐8, CCL2, CXCL8 and CXCL12, and enable tumour metastasis by up‐regulated N‐cadherin and Snail, whereas down‐regulated E‐cadherin." (PMID 32588948, 2020). "It is regulated by endotoxin and some cytokines including TNF-α, IL-1β, and IFN-γ in vitro and in vivo; ICAM-1 plays an important role in promoting adhesion at the site of inflammation, controlling tumor progression and metastasis, and regulating immune responses in the body." (PMID 32089647, 2020). "Neutrophils could secrete TNF-alpha, VEGF, and interleukin, thus to promote tumor cell proliferation and angiogenesis." (PMID 33097053, 2020). "Co-administration of AAVP-TNF and LCL161 to M21 human xenograft mice led to increased expression of TNF specifically in tumor tissue, and not in healthy organs." (PMID 32053868, 2020). "Interestingly, of all cytokines measured, TNFα and TGF-β2 also correlated significantly with mouse tumor burden." (PMID 32849651, 2020). "Immune cells stimulated with IL-15 produce high levels of IFN-γ and TNFα, and IL-15’s strong immune-stimulatory activity coupled with an apparent lack of toxicity made it a promising candidate for tumor therapy." (PMID 33133514, 2020). "CD8+ T cells from tumor‐bearing mice lacking USP44 also were found to express markedly higher levels of TNFα and significantly higher levels of the effector molecule granzyme B than their wild‐type counterparts." (PMID 32644293, 2020). "Finally, IHC analysis of tumor tissues in 120 patients showed that the TAM and the expression levels of IL-6 and TNF-α in tumor cells of FOBT-positive patients were significantly higher than those in FOBT-negative patients." (PMID 33643891, 2020). "Inflammatory cytokines such as tumor necrosis factor-alpha (TNF-α), transforming growth factor-beta (TGF-β), interleukin-6 (IL-6) and other cytokines/chemokines have been known to enhance tumor proliferation, activate epithelial-to-mesenchymal transition (EMT) and promote metastatic potential." (PMID 33212880, 2020). "To investigate whether the synergistic effect of TNF and IFN‐γ depends on direct actions on tumor cells or on host cells, we generated IFN‐γ‐insensitive B16Bl6 tumor cells (B16‐dnIFN‐γR)." (PMID 31912630, 2020). "Research on TNF anti‐tumor activity, in contrast, has not yet resulted in a therapeutic breakthrough." (PMID 31916677, 2020). "Cytokines, such as tumor necrosis factor alpha (TNF-α), interleukin-6 (IL-6), and transforming growth factor-beta (TGF-β), are the major mediators which are responsible for interchanging among cells in the tumor microenvironment." (PMID 32123532, 2020). "Thus, TF expression is induced both in normal cells (mostly vascular or fibroblastic-type cells and monocytes after injury or infection) and in tumor cells by a variety of inflammatory and growth factors including VEGF, TNFα, IL-1β, IL-6, or IL-8." (PMID 32152404, 2020). "Despite having a TNF‐R1‐expressing tumor, the antitumor effect of TNF was completely absent in either TNF‐R1−/− or p55cneo/cneo mice." (PMID 31912630, 2020). "Tumor necrosis factor (TNF) superfamily consists of 19 ligands and 29 receptors and is related to multiple cellular events from proliferation and differentiation to apoptosis and tumor reduction." (PMID 32612943, 2020).
tumor (continued). "In this regard, TNFα maintains C2C12 cultures in a proliferative setting, which could partially explain the accumulation of SCs observed in the muscle of tumour‐bearing mice." (PMID 32103619, 2020). "In human iCCA tissues TNF-α is mainly expressed in infiltrating macrophages, while CXCR4 is present in cancer cells but not in non-neoplastic ducts and CXCL12 in stromal fibroblasts and, to a lesser extent, in tumor cells." (PMID 32784743, 2020). "In support of IL-10 tumor suppressor action, several studies observed that IL-10 was able to induce AML blasts apoptosis in vitro probably through the inhibition of proinflammatory cytokines production, such as IL-1α, IL-1β, IL-6, GM-CSF and TNF-α." (PMID 32443460, 2020). "Moreover, the autologous infusion of tumor antigen specific CD4+ Th1 lymphocyte can promote senescence in pancreatic tumor cells by releasing SASP factors such as IFNγ and TNFα." (PMID 32370259, 2020). "A recent study demonstrated that the interaction of TNF-α and angiotensin II in HCC cells could enhance tumor proliferation, migration and invasion via the regulation of G protein-coupled receptor kinase 2 (GRK2)." (PMID 32722054, 2020). "Furthermore, immune cells activated by IL-15 have been shown to have a high capacity for cytokine secretion, including IFN-γ, TNF-α, TNF-β, GM-CSF, and IL-10, resulting in apoptosis of tumor cells." (PMID 33133514, 2020). "Following tumor infiltration, CD8+ TIL performs antitumor effector functions, through the exocytosis of perforin and cytotoxic granzymes, or through the release of interferon (IFN)-γ and tumor necrosis factor (TNF)-α." (PMID 32630708, 2020). "In this way, AAT down regulates tumor necrosis factor-induced apoptosis, suggesting that elevated AAT levels may, therefore, promote cell survival and tumor growth." (PMID 32630147, 2020). "Like TNF-α, IL-6 facilitates tumor development by promoting the conversion of non-cancerous cells into cancer stem cells." (PMID 32283655, 2020). "Here, IOP can inhibit the production of IL-6, TNF-α and COX-2 in colon tissue, suggesting that this may be one of the potential mechanisms by which IOP exerts its anti-tumor effect." (PMID 33603669, 2020). "Transduction using iaIL-12 increased the production of IFN-γ, TNF-α, and IL-2 as compared with transduction using negative control (iGFP) when T cells were cocultured with tumor cells expressing the target antigen (SS4050 and CaSki)." (PMID 31959727, 2020). "Analysis of tumor CD8+ T cell responses upon T-cell receptor stimulation demonstrated that EBAT treatment induced the highest proportion of CD8+ T cells producing IFNγ and TNFα, as well as multifunctional IFNγ/TNFα double positive T cells." (PMID 33747894, 2020). "In line with this notion, blockade of the ActRIIB receptor to inhibit Mstn signaling prevented cachexia in C26 tumor bearing mice, without affecting increased circulating levels of IL-6, TNF-α, and IL-1β." (PMID 33329046, 2020). "We found that tumor endothelial cells from agonistic CD40 mAb treated tumors upregulated biological processes such as “inflammatory response”, “response to IFNγ”, “positive regulation of leukocyte chemotaxis” and “positive regulation of TNF production”." (PMID 32231867, 2020). "TNF-α is also involved in the increased expression of adhesion molecule (such as VCAM-1 or P-selectin) on the endothelium of tumor vessels, leading to the necrosis of tumor." (PMID 32102503, 2020). "It has previously been shown that Nr2f6−/− T cells are hyper-reactive in regard of cytokine production (IL-2, IFNγ, TNFα) as those cytokines are direct target genes of NR2F6-dependent transcriptional repression leading to an improved anti-tumor immune contexture at the tumor site." (PMID 31937317, 2020). "Moreover, TNF-α, IL-6, and several typical differentially expressed phosphorylated proteins (such as p-CCNB1, p-FOXO3, and p-STAT3) in tumor tissues, tumor cell viability, and cell cycle arrest assay in vitro further verify the results of IPA." (PMID 33344655, 2020).